MYC (MYC proto-oncogene, bHLH transcription factor)
Diseases named in the same sentence as MYC in open-access papers (continued):
Sharing a sentence is not in itself a finding about the gene and the disease.
cancer (continued). "The ability of MYC to switch between its promoter‐bound state and its multimeric form is essential for its function in cancer cells, enabling it to overcome the transcriptional and replication stress that it encounters during rapid proliferation." (PMID 40488968, 2025). "As an oncogenic protein accelerating the progression of multiple human cancers, c-MYC dysregulation is positively correlated with poor clinical outcomes among cancer patients." (PMID 39736850, 2025). "Previous work from our group has demonstrated significant upregulation of MYC signaling and cancer stem cell markers in neuroendocrine-like PCa models resistant to therapy." (PMID 40361461, 2025). "BRD4 bromodomain inhibitors including JQ1 and I-BET-726 have gained particular interest and have been shown to transcriptionally inhibit MYC and exert therapeutic activity against several cancers." (PMID 39706891, 2025). "Given that c-MYC overexpression is one of the most common molecular abnormalities across a wide spectrum of human cancers, the stabilization of G-quadruplex structures within its promoter by small molecules has emerged as a promising antitumor strategy." (PMID 41226615, 2025). "Our previous study provided strong experimental and computational evidence that the miR-17/92 cluster plays a central role in MYC dosage compensation in aneuploid cancer cells." (PMID 40940795, 2025). "The MYC oncogene is activated in most cancers, where it enhances cancer cell-intrinsic processes such as proliferation, metabolism, invasion, apoptosis, and autophagy, while inhibiting protective mechanisms like differentiation and senescence." (PMID 40244089, 2025). "In digestive system tumors, editing of AZIN1 delays c-MYC degradation and upregulates IL-8, endowing cancer cells with stemness and promoting angiogenesis." (PMID 41446042, 2025). "Stemness of cancer stem cells (CSCs) is associated with expression of the Yamanaka OCT4, SOX2, KLF4 and MYC (OSKM) pluripotency factors that confer lineage plasticity and dedifferentiation." (PMID 40764753, 2025). "Ferroptosis in turn activates ODC expression through iron overload-WNT/MYC signaling, resulting in increased polyamine synthesis, thus generating a positive feedback loop in cancer cells." (PMID 40603833, 2025). "Our results showed strong and diffuse staining across cancer tissues, with markedly higher levels of c-MYC methylation compared to their normal counterpart." (PMID 40588481, 2025). "MYC and CCND1 have been well-associated with cancer through many studies, and their respective proteins play important roles in the cell cycle." (PMID 40770488, 2025). "FOXR2 promotes tumor growth by activating MYC transcription in different human cancer cell lines and tissues, such as breast, lung, and liver." (PMID 39866234, 2025). "MYC OG, also known as c-MYC, is a central controller of numerous biological processes and is frequently activated in human cancers." (PMID 40227591, 2025). "There is evidence that in different cancers, IGF2BPs increase MYC expression, stabilizing the transcript and preventing its degradation." (PMID 40507925, 2025). "Although MYC overexpression induces transcriptional and replication‐associated stress, recent studies have paradoxically identified MYC as a key resilience factor that protects cancer cells from these stressors." (PMID 40488968, 2025). "We show that CPSF1 amplification, although co-occurring with MYC amplification, can independently change alternative polyadenylation (APA) patterns and dysregulate cancer-associated gene signatures." (PMID 41463412, 2025). "For instance, Let‐7 family members have been reported to modulate oncogenes like RAS, HMGA2, and MYC in other cancer contexts, raising the possibility of unintended gene regulation in HCC." (PMID 40530890, 2025).
cancer (continued). "Core regulatory circuitry (CRC) transcription factors (TFs), whose effects are increased by MYC, define cancer cell‐type identity and drive oncogenes in cancer." (PMID 39119816, 2025). "The PAAD ColX module is enriched for targets of the transcription factor NME2, which regulates cancer cell proliferation in a variety of contexts through activation of MYC." (PMID 39939916, 2025). "This interplay, especially involving miR-17, miR-19a, and miR-20a, contributes to MYC dosage compensation in aneuploid cancer cells, allowing them to maintain oncogenic activity despite genomic instability." (PMID 40940795, 2025). "This article advocates for a multi-dimensional, biomarker-guided approach to MYC targeting, emphasizing rational drug combinations and continued innovation to overcome resistance and improve outcomes in MYC-driven cancers." (PMID 40365020, 2025). "The aim of this study was to explore how MYC—a major oncogenic transcription factor with intimate ties to cancer—influences SCCOHT biology." (PMID 40647552, 2025). "It targets CREPT and RNAPII activity and the transcription of MYC, cyclin D1, and other oncogenes that are involved in cancer progression." (PMID 40723282, 2025). "In SCCOHT tumors and other cancers marked by SWI/SNF subunit mutation, MYC target genes are recurrently activated, pointing to a relationship between SWI/SNF and MYC that has yet to be fully explored." (PMID 40647552, 2025). "As expected, gene set enrichment analysis (GSEA) of dormant cancer cells revealed a decreased enrichment of cell cycle mediators including targets of E2F and MYC, as well as mTOR signaling." (PMID 40568095, 2025). "Nonetheless, the interaction of NOTCH1 in the locus of the MYC gene requires further investigation and proof regarding its direct connection with epichaperome formation in leukemias and other cancers." (PMID 39936995, 2025). "In G401 cells, the depletion of MYC results in a similar decreased level of both ATR and RAD51, suggesting that MYC generally controls DNA repair protein expression in SWI/SNF-altered cancer cell lines, as has been seen in other cancers." (PMID 40647552, 2025). "MYC amplification promotes cancer by inducing transcription via enhancers and super-enhancers, which in turn produces topological constraints that interfere with efficient transcription." (PMID 40075567, 2025). "The overexpression of MYC in PC samples reinforces its role as an oncogene in the progression of PC, which is frequently overexpressed in most cancers, especially in somatic genetic alterations such as translocations and gene amplifications." (PMID 41296417, 2025). "MYC promotes invasiveness of cancer cells in SCLCs and NSCLCs, facilitating their ability to migrate and invade surrounding tissues by enhancing VEGF and TNF-β production." (PMID 40869000, 2025). "The enhanced invasiveness of cancer cells following PPARδ activation by GW0742 was reversed by MYC knockdown or PGC1A overexpression, suggesting that an elevated MYC/PGC1A ratio is essential for invasion." (PMID 40607925, 2025). "The pathogenesis of different cancers includes MYC overexpression which results from increased histone acetylation." (PMID 40959208, 2025). "Given the common dysregulation of the MYC oncogene in human cancer, probing the mechanism of the role of MYC in cell cycle control is important." (PMID 40612865, 2025). "In MYC-amplified cancer models, BET inhibition downregulated MYC-dependent transcription programs and induced differentiation and apoptosis." (PMID 41614813, 2025). "Our findings establish a novel therapeutic modality targeting translational control via mRNA relocalization, with enhanced efficacy against cancer cell lines exhibiting high dependency on an RNA-binding protein which regulates MYC mRNA translation, RBM42." (PMID 40943063, 2025).
cancer (continued). "This vulnerability is evidenced by the differing interaction kinetics of Hsp90 with small molecules between normal and transformed cells that lack the MYC gene-reinforcing influence and cancer cells with the MYC reinforcement." (PMID 39936995, 2025). "For instance, the bacterial Lon protease has been engineered for selective degradation of MYC protein in cancer cells." (PMID 40365020, 2025). "BRD4 commonly associates with cancer-maintenance genes (e.g. MYC, RUNX1) that are decorated with high-level acetylation, which leads to selective cancer dependency on BRD413." (PMID 39651888, 2025). "Of particular interest is CDK9′s role as a regulator of MYC, a well-studied transcription factor that promotes the growth and progression of many cancer types." (PMID 40163908, 2025). "We therefore propose that rearrangement at PVT1 is a sophisticated mechanism exploited by cancer cells to sculpt the oncogenic landscape of MYC-driven malignancies." (PMID 40027648, 2025). "Ultimately, given MYC's pervasive role in cancer, it is crucial to contemplate the potential adverse effects of MYC inhibition, such as premature aging." (PMID 40290126, 2025). "The knockdown of CREPT expression impairs MYC transcriptional activity downstream of the Wnt/β-catenin signaling pathway, which leads to the inhibition of cancer cell proliferation." (PMID 40723282, 2025). "This work establishes a novel therapeutic strategy to inhibit MYC translation mediated by hnRNPK, offering a translationally targeted approach to cancer therapy." (PMID 40943063, 2025). "We next analyzed the direct in vivo anti-cancer activity of CBL0137 using the MYC-high MDA-MB-231 TNBC cells orthotopically injected into immunocompromised NSG mice." (PMID 39706891, 2025). "Under conditions of replication stress or compromised repair capacity, these topoisomerase-mediated transient breaks can convert to permanent DNA lesions, directly contributing to the genomic instability that characterizes MYC-driven cancers." (PMID 41561634, 2025). "In cancer biology, glycolysis, the metabolic pathway that converts glucose into pyruvate, and the MYC oncogene are frequently reprogrammed to support the rapid proliferation and survival of cancer cells." (PMID 41234356, 2025). "Modulation of cancer immune surveillance by oncogenic c-Myc: The transcription factor MYC regulates self-renewal, differentiation, proliferation, and apoptosis and directly regulates the expression of PD-L1 and CD47." (PMID 39851497, 2025). "For example, recent preclinical studies demonstrated that anti-MYC nanobodies effectively penetrate cancer cells, selectively binding intracellular MYC protein and disrupting its transcriptional activity." (PMID 40365020, 2025). "MYC is a transcription factor that is overexpressedin most cancers.MYC is composed of an N-terminal transactivation domain, a C-terminalbasic-helix–loop–helix leucine zipper DNA binding domain,and a central region." (PMID 40043012, 2025). "On the other hand, it is well known that MYC is a master regulator of cancer cell proliferation, metabolism and immune evasion, with pleiotropic effects on cell cycle, DNA repair, and multiple metabolic pathways." (PMID 40276769, 2025). "Yet, in the cancer cell context, MYC overexpression drives a profound rewiring toward survival, directly inducing DNA repair pathways." (PMID 41561634, 2025). "For example, MYC enhances cellular antioxidant capacity and suppresses ferroptosis in cancer stem cells by activating CPT1A expression, which in turn activates the NRF2/GPX4 system and reduces phospholipid polyunsaturated fatty acids via ACSL4 downregulation." (PMID 40732268, 2025). "While our findings highlight the therapeutic potential of targeting PA2G4 in MYC-driven cancers, several important limitations remain." (PMID 41002386, 2025).
cancer (continued). "Studies have found that there is a complex interaction between MYC and DNA damage repair network, which provides a new perspective for developing new cancer treatment strategies." (PMID 40290723, 2025). "The precise functions and regulatory mechanisms of MYC require further elucidation, which would be beneficial for precision medicine in cancer treatment." (PMID 40290126, 2025). "Numerous studies have revealed the regulatory effects of circRNAs on MYC in various cancers, yet the role of hsa_circ_0003611 in MYC activation during the transformation of MSCs into OS cells has not been reported." (PMID 41318550, 2025). "Among these, MYC is a well-established oncogene frequently dysregulated in various cancers, including BCa." (PMID 40280416, 2025). "The shift in balance towards MYC’s repair-promoting functions is a survival strategy for cancer cells but also their potential downfall." (PMID 41561634, 2025). "Although direct targeting of MYC remains challenging due to its complex molecular interactions, its critical role in cancer cell dependency makes it an attractive therapeutic target." (PMID 41155227, 2025). "siRNA silences the mRNA expression of the oncogene c-MYC, thereby inhibiting cancer cell proliferation, differentiation, and apoptosis." (PMID 40943628, 2025). "As a critical transcription factor, c-MYC plays a pivotal role in the initiation and progression of numerous cancers." (PMID 41184982, 2025). "Recent investigations encompassing pan-cancer analyses have elucidated that the reprogramming of MYC gene enhancers is prevalent in a diverse array of human tumors." (PMID 40032852, 2025). "Inhibitors like I-BET726 and JQ1, which target bromodomain 4 (a key factor in MYC transcription), have shown promise in blocking MYC transcription and increasing cancer cell immunogenicity by suppressing PD-L1 expression." (PMID 40552293, 2025). "Despite extensive research on the miR-34b/MYC axis across various diseases, including cancer, the specific role of miR-34b in brain injury and its therapeutic implications are still being explored." (PMID 39129166, 2025). "Previous studies have demonstrated that MYC transcriptionally upregulates PD-L1 in multiple cancer types, with direct binding to the PD-L1 promoter region driving its expression." (PMID 40510369, 2025). "Comprehensive analysis of transcriptome sequencing results pertaining to RBPMS and ANKRD10 revealed a potential interplay between RBPMS and ANKRD10-2 in influencing cancer progression, possibly through their influence on MYC target gene expression." (PMID 40044952, 2025). "In this context, MYC’s predominant role is damage mitigation, helping cancer cells repair the very stress that uncontrolled proliferation creates." (PMID 41561634, 2025). "Nuclear-retained CCAT1-L functions not only as a cancer biomarker but also as a key driver of tumorigenesis, primarily through its regulation of the MYC oncogene." (PMID 40521240, 2025). "The 4EBP1 inhibitor antagonizes eIF4E by signal transduction pathways that phosphorylate and inactivate of 4EBP1, suggesting the potential importance of eIF4E as a MYC regulatory target in cancer." (PMID 39779613, 2025). "Aberrations in the MYC locus or deregulation in MYC pathways are identified in more than half of all human cancers." (PMID 41170752, 2025). "These alterations increase the synthesis of MYC, a critical transcription factor that drives the reprogramming of normal cells into cancer cells, thereby enhancing their proliferation and resistance to chemotherapy." (PMID 39858030, 2025). "MYC is among the most frequently dysregulated oncogenes in human cancer, yet its direct targeting remains a significant challenge." (PMID 41025936, 2025). "The MYC gene regulates cell cycle activation, anti-apoptosis, metabolism modulation and the molecular characteristics of cancer stem cells." (PMID 40615564, 2025).
cancer (continued). "c-MYC is an oncogenic transcription factor that is often constitutively expressed in many cancer types and coordinately regulates a network of proteins involved in cell cycle, proliferation, and metabolism." (PMID 40037707, 2025). "MYC is dysregulated in approximately 70% of human cancers, strongly suggesting its essential function in cancer." (PMID 40290126, 2025). "Although MYC activation of glycolysis in cancer cells is well documented, its control over mitochondrial oxidative phosphorylation (OXPHOS) is poorly understood." (PMID 40668928, 2025). "Mechanistically, we demonstrated that PA2G4 is essential for maintaining c-MYC protein stability and cell viability across various c-MYC-expressing cancer cell lines." (PMID 41002386, 2025). "A unique feature of some tumors from group 3 MB is gene fusions involving MYC and Plasmacytoma Variant Translocation 1 (PVT1), a long non-coding RNA implicated in a variety of human cancers." (PMID 40365336, 2025). "Multiple pieces of evidence indicate that the oncogene MYC can promote the occurrence, progression, and metastasis of various malignant tumors, including glioblastoma, triple-negative breast cancer, and OS." (PMID 39897587, 2025). "Both drugs individually had only limited effects on KRASG12V/MYC cancer cells, while a combination strongly impaired their proliferation." (PMID 40550880, 2025). "PF-3758309 inhibited the activities of PAK and other kinases and reduced the phosphorylation and expression of key proteins, like c-MYC, which are known to be important for the proliferation of cancer cells." (PMID 40082888, 2025). "The development of MYC-focused therapies is particularly compelling given the oncogene’s central role in driving tumorigenesis across various cancers, including AT/RT." (PMID 40076599, 2025). "These MYC-amplified cancer models include various cancer types, such as leukemia, lymphoma, and certain solid tumors, highlighting the broad applicability of this approach." (PMID 41614813, 2025). "This suggests the MYC-driven oncogenic transformation of cancers, resulting in dependence on MYC expression." (PMID 40282497, 2025). "Activation of ERα permits the expression of factors such as MYC and CCND1, which have oncogenic potential and increase the risk of cancer cell proliferation and DNA damage in response to estrogen." (PMID 40708058, 2025). "Consistent with this, inhibition of topoisomerase 1 leads to abnormal R-loop accumulation and synthetic lethality with MYC-driven cancer." (PMID 40075567, 2025). "On the other hand, different from co‐cultured (E‐M2) or MYC overexpression alone (M‐V) cells, only M‐M2 trained cancer cells exhibited MP transcriptional landscape alterations in markers associated with MP characteristics, such as EMT and cell adhesion." (PMID 39899538, 2025). "Its synthesis commences from a CUG initiation codon located within the transcript of the MYC oncogene, and it fulfills essential functions in both the initiation and progression of diverse cancer types." (PMID 40628713, 2025). "EXOSC5 upregulates NTN4 expression, activating c-MYC through the integrin β1/FAK/SRC pathway to sustain cancer stem cell activity." (PMID 41235257, 2025). "We selected MycCaP because it is a robust MYC-driven cancer model that can be transplanted into syngeneic immunocompetent mice, facilitating both in vitro and in vivo analyses." (PMID 40668928, 2025). "One of the genes responsible for the metabolic reprogramming of cancer cells is MYC, which, among other functions, enhances glycolysis." (PMID 40507925, 2025). "Epichaperome hyperconnectivity is reinforced by the downstream effect of the MYC gene, ensuring the cancer cell’s survival." (PMID 39936995, 2025). "While SIRT1 can promote cancer progression by enhancing c-MYC activity, DBC1 counteracts this process, thereby exhibiting anticancer effects." (PMID 40692869, 2025).